SPDL1 (spindle apparatus coiled-coil protein 1)
Diseases named in the same sentence as SPDL1 in open-access papers (continued):
Sharing a sentence is not in itself a finding about the gene and the disease.
tumor (185 papers, 2015 to 2026). "Decreased SPDL1 expression in CRC cells significantly increased tumor development, and it was found to be associated with poor prognosis in patients with cancer." (PMID 39196978, 2024). "In this review, we provide an overview of studies that reveal the characteristics of SPDL1 and of the protein encoded by it, as well as its biological and tumor-promoting functions." (PMID 38623460, 2024). "Previous studies have revealed that SPDL1 was associated with digestive tract malignancies and tumor progression." (PMID 39196978, 2024). "It was demonstrated that SPDL1 remained significantly associated with OS after adjusting for age, gender, and tumor stage." (PMID 35163739, 2022). "In the TCGA cohort, SPDL1 was overexpressed in tumor tissue and positively associated with improved survival, chromosome instability phenotype, and various GIN markers." (PMID 35163739, 2022). "Abnormal expression of SPDL1 may cause genomic instability, which accelerates tumor progression, invasion, and metastasis." (PMID 39865406, 2025). "However, an in silico study showed that SPDL1 upregulation was significantly associated with worse overall and disease-free survival, as well as advanced tumor phase." (PMID 39148981, 2024). "Both in vitro and in vivo, the Nanot nanoparticles reduced circulating levels of sPDL‐1 and demonstrated significant tumor size reduction in sPD‐L1 secreting tumors." (PMID 40324952, 2025). "Tumor xenograft model assay also demonstrated that knockdown of SPDL1 suppressed tumor growth in vivo." (PMID 39148981, 2024). "Concerning the sPDL1, its release was correlated with a poor prognosis and seemed to be tumor-type dependent." (PMID 38570798, 2024). "The overexpression of SPDL1 in tumor tissues was found to be related to improved survival, CIN phenotype, and different types of GIN markers." (PMID 38623460, 2024). "Overexpression of SPDL1 was detected in the tumor tissues of patients with OSCC, and its high expression correlated with the stage, tumor grade, and treatment modality and shortened the survival time of patients." (PMID 38623460, 2024). "SPDL1 is considered a pro-oncogene that expedites tumor cell proliferation, invasion, and metastasis, and is closely associated with the prognosis of tumor patients." (PMID 38623460, 2024). "The methylation degrees of the SPDL1 promoter in tumor tissues were higher than that in normal tissues in BLCA, COAD, CESC and ESCA." (PMID 35093072, 2022). "The top 100 genes related with SPDL1 expression of all tumor tissues in TCGA were obtained by the GEPIA2 tool." (PMID 35093072, 2022). "It was demonstrated that SPDL1 remained significantly associated with OS after adjusting for age, gender, grading, resection margin, AJCC TNM stage, and tumor location." (PMID 35163739, 2022). "The comparison with adjacent normal tissue revealed an up-regulation of SPDL1 protein in a subset of tumor samples (48.84%), and these had better prognosis than the SPDL1-low expression counterpart even after adjusting for multiple confounders." (PMID 35163739, 2022). "Considering the heterogeneity of different tumor types, a pan-cancer analysis is needed to get a comprehensive understanding of SPDL1." (PMID 35093072, 2022). "The correlation between the immune infiltration of CD8+ T-cells and SPDL1 expression in tumor tissues (BRCA, HNSC-HPV+, LIHC, LUSC, PAAD, PRAD, SKCM, THYM, UCEC and UVM) was found to be statistically significant based on four algorithms." (PMID 35093072, 2022). "The SPDL1 expression was positively correlated with the immune infiltration of CD8+ T-cells and cancer-associated fibroblasts (CAFs) in most of the tumor types." (PMID 35093072, 2022). "SPDL1 was overexpressed in most tumors compared with adjacent normal tissues, and SPDL1 expression was significantly correlated with the prognosis in most tumor types." (PMID 35093072, 2022).
tumor (continued). "The comparison with adjacent normal tissue revealed a high expression of SPDL1 protein in a subset of tumor cases (48.84%), and these had better prognosis than the SPDL1-low expression counterpart even after adjustment for multiple confounders." (PMID 35163739, 2022). "We found cyclin F, RRM2, and SPDL1 to be overexpressed at both protein and mRNA levels in tumor tissues compared to respective controls." (PMID 33670609, 2021). "According to this analysis, overexpression of SPDL1 protein was found to be an independent predictor of improved OS after adjustment for age at diagnosis, gender, histologic grade, tumor stage, VI and PNI, and study (HR = 0.36, 95% CI 0.16–0.80; p = 0.01)." (PMID 33670609, 2021). "In tumor tissues, SPDL1 was mainly detected in the cytoplasm, but sporadic membranous–cytoplasmic staining pattern occurred, while the adjacent non-cancerous tissues showed solely cytoplasmic immunoreactivity." (PMID 33670609, 2021). "Our study for the first time compared the correlation between tumor PD-L1 IHC profiles and levels of Exo-PD-L1 and levels of sPDL1, respectively." (PMID 31665020, 2019). "Correlation between Exo-PD-L1, sPDL1 concentration and several clinicopathological characteristics (age, gender, smoking status, histologic subtype, tumor size, lymph node status, distant metastasis and TNM stage) were investigated." (PMID 31665020, 2019). "sPDL1 is thought to be a circulating biologically active protein which is released from PD-L1-positive tumor cells or immune cells." (PMID 27780932, 2016). "The recurrent cases, which are believed to have low tumor burden, showed a lower level of sPDL1 than initially unresectable cases." (PMID 27780932, 2016). "SPDL1 (Spindly), known for its role in mitotic checkpoint control, may contribute to tumor evolution through effects on genomic stability." (PMID 41321310, 2025). "These processes are related to genome composition and cell proliferation, indicating that abnormal expression of SPDL1 may cause genomic instability (GIN), which may lead to disease development and tumor progression." (PMID 38623460, 2024). "SPDL1 also increases sensitivity to low-dose MTAs and reduces drug resistance in tumor cells." (PMID 38623460, 2024). "Interestingly, SPDL1 exhibits tumor heterogeneity in CRC and PDAC and inhibits the development of these cancers." (PMID 38623460, 2024). "In vivo, knockdown of SPDL1 inhibited the tumor growth of HCC cells." (PMID 39148981, 2024). "Rescue assay determined that FNTB played a tumor promoting role in SPDL1-trigger HCC cell growth." (PMID 39148981, 2024). "The tumor volume and weight were decreased in SPDL1 knockdown group comparing with shCtrl group." (PMID 39148981, 2024). "The purpose is to explore whether sPD1 and sPDL1 are related to the imbalance of ILC1/ILC2 and M1-like/M2-like monocytes in the circulation and to provide a theoretical and experimental basis for sPD1 and sPDL1 as tumor predictors." (PMID 36479137, 2022). "In addition to its role in normal tissue cells, SPDL1 is also involved in the tumor growth and prognosis." (PMID 35093072, 2022). "The genetic alteration status of SPDL1 was investigated in different tumor types of the TCGA." (PMID 35093072, 2022). "Previous therapies and different molecular signatures from several tumor types could also influence the release of sPDL-1 in the blood." (PMID 36430974, 2022). "This may reflect the tumor tissue-specific role of SPDL1 and/or stage-specific, tumoral genetic background-specific or severity-dependent differences in the prognostic impact of genomic instability among various cancers." (PMID 35163739, 2022). "In addition, the correlation between SPDL1 expression and the estimated infiltration value of CAFs for the tumor tissues of BRCA-LumA, ESCA, HNSC-HPV-, KIRC, KIRP, MESO, PAAD, PCPG and THCA was observed statistically positive." (PMID 35093072, 2022).
tumor (continued). "Notably, stratification by SPDL1 expression within two subgroups of different tumor stage (stage II and stage III–IV) identified patients with significantly different OS within the same stage subgroup." (PMID 35163739, 2022). "sPDL1 may be a marker for tumor burden of PD-L1-positive disease, and/or sPD-L1 may be a surrogate for other mechanisms of immunotherapy-resistant disease, such as a protumorigenic microenvironment." (PMID 35131863, 2022). "In the recent in silico study, SPDL1 has been identified as one of the key candidate genes differentially expressed in PDAC, whereby the upregulation of its mRNA was significantly associated with a worse OS and DFS, as well as the advanced tumor stage." (PMID 33670609, 2021). "Therefore, we demonstrate that SPDL1 knockdown inhibited tumor growth in vivo." (PMID 39148981, 2024). "As revealed by an integrative analysis of research, the expression of SPDL1 in CRC was significantly associated with GIN phenotypes (including the CIN/aneuploidy score) and was related to the expression of DNA break repair (MMR) genes, affecting the proliferative activity of tumor cells." (PMID 38623460, 2024). "SPDL1 is also an active circulating protein that induces apoptosis of CD8+ T cells and impairs the ability of these effector cells to kill tumor cells." (PMID 37915003, 2023). "In contrast, the methylation levels of SPDL1 in HNSC, KIRC, KIRP, SARC, TGCT and UCEC tumor tissues were lower than that in normal tissues." (PMID 35093072, 2022). "SPDL1 was identified as tumor infiltration CD8+ T cell-related genes in a prognostic model in LUAD, which indicate the potential relation of SPDL1 and immunity." (PMID 35093072, 2022). "Furthermore, sPDL1 could contribute to the immune evasion mechanism, treatment resistance, and worse prognosis as well as sTIM3 values below the median (7972 pg/ml), reflecting the role attributed to their transmembrane form when expressed by tumor cells." (PMID 36405727, 2022). "Given that cyclin F, RRM2, and SPDL1 are considered GIN-related proteins, we also analyzed their expression in relationship to tumor aneuploidy score and fraction genome altered (TCGA cohort) or MSH6 protein level (our cohort)." (PMID 33670609, 2021). "It has been hypothesized that the effects of SPDL1 on tumors may involve enhanced CIN, which accelerates tumor progression, invasion, and metastasis by affecting GIN and driving chromosomal segregation." (PMID 38623460, 2024). "Cytoplasmic SPDL1 was characterized by ubiquitous, diffuse staining on tumor cells but not in a uniform intensity." (PMID 35163739, 2022). "Both SPDL1 protein and mRNA levels were markedly up-regulated in tumor tissues relative to non-cancer normal tissues (p < 0.0001)." (PMID 33670609, 2021). "Stage II/III/IV tumor had significantly higher sPDL1 levels than stage I while ANOVA test showed that sPDL1 expression was not different between each group." (PMID 31665020, 2019). "Interestingly, another study showed that serum soluble PD-L1 (sPD-L1) concentration was several-fold higher in HBV-related HCC than in healthy control, a significant difference, while sPDL1 was positively correlated with tumor PD-L1 expression." (PMID 32770259, 2021). "In our study, sPDL1 did not correlate with any clinicopathologic features except for tumor size." (PMID 31665020, 2019). "In summary, our results supported the notion that altered SPDL1 expression in CRC tissue might predict patient outcome, and mechanistically this was likely attributable, at least partially, to tipping the balance of chromosomal instability toward the detriment of tumor overall longevity." (PMID 35163739, 2022). "However, the subgroup meta-analysis conducted on these two tumor types did not have the statistical power to consider whether or not sPDL1 was a prognostic factor." (PMID 36430974, 2022).
tumor (continued). "As far as we know, there are no other reports on the impact of SPDL1 protein on disease outcome and clinical variables of cancer patients, and thus further studies are required to determine whether the role of Spindly in human cancers is tumor-type dependent." (PMID 33670609, 2021). "Regardless of tumor type, patients with values of sTIM3, IFNα, IFNγ, IL1β, IL1α, IL12p70, MIP1β, IL13, sCD28, sGITR, sPDL1, IL10 and TNFα below the median had longer overall survival (p<0.05)." (PMID 36405727, 2022). "SPDL1 expression level was significantly correlated with maximum standardized uptake value (SUVmax), SUVmean, and total legion glycolysis (TLG), but was not correlated with metabolic tumor volume, tumor diameter, and tumor invasion depth of PET/CT." (PMID 35664322, 2022).
cancer (126 papers, 2015 to 2026). A tumor composed of atypical neoplastic, often pleomorphic cells that invade other tissues. "An analysis of the common genetic background of IPF and cancer based on the data from the Finland-Finland Study and the UK Biobank, based on two large biobanks, revealed that SPDL1 is associated with a locus inextricably correlated with IPF." (PMID 38623460, 2024). "The high-risk scores of SPDL1-related long non-coding RNAs were significantly correlated with overall survival and cancer progression in patients with ESCC (P < 0.05)." (PMID 39196978, 2024). "Here, we performed this pan-cancer analysis to evaluate the expression and prognostic value of SPDL1 and gain insights into the association between SPDL1 and immune infiltration." (PMID 35093072, 2022). "SPDL1 was upregulated in ESCA, and increased SPDL1 expression was associated with poor prognosis, and cancer progression." (PMID 35664322, 2022). "SPDL1 is considered to play an important role in the cell cycle, which is associated with the progression of many cancers." (PMID 35093072, 2022). "In addition, high SPDL1-related lncRNA risk scores were significantly associated with OS and cancer progression in patients with ESCC." (PMID 39196978, 2024). "In summary, SPDL1 was widely overexpressed in most cancer types, meanwhile its overexpression is mostly associated with poor prognosis, which indicated that SPDL1 may promote tumorigenesis and play a pivotal role as a potential oncogene." (PMID 35093072, 2022). "In addition, we explored the potential association between SPDL1 gene alteration and clinical survival in patients with different cancer types." (PMID 35093072, 2022). "Hence, SPDL1 is suspected to underlie genomic (in-)stability in human cancers, yet its exact roles in these diseases remain largely underexplored." (PMID 35163739, 2022). "Interestingly, the variant of SPDL1 reduce the incidence of different cancer types due to lower chromosomal alterations accumulated over time." (PMID 35093072, 2022). "Unlike sPD-1, sPDL-1 can bind with PD-1 on immune cells and inactivate them; increased levels of sPDL-1 in cancer patients correlate with worse prognosis." (PMID 40109334, 2025). "Spindle apparatus coiled-coil protein 1 (SPDL1) is involved in the development of various cancers in humans." (PMID 39148981, 2024). "Nevertheless, our TE-1 cell model experiments using the CCK-8 assay, EDU staining, and transwell assay confirmed that the inhibition of SPDL1 expression significantly impaired cancer cell proliferation, migration, and invasion." (PMID 39196978, 2024). "Analysis of a pancancer database revealed that SPDL1 expression is elevated in most malignant tumors, including OSCC and esophageal and breast cancers." (PMID 38623460, 2024). "Recent studies have indicated that high expression of SPDL1 participates in the progression of human cancers." (PMID 39148981, 2024). "In this pan-cancer study, we provided a comprehensive and systematic characterization of SPDL1, and demonstrated the oncogenic role of SPDL1 in cancers." (PMID 35093072, 2022). "In the future, more experiments and large-scale clinical trials are needed to further validate these findings and to explore the follow-ups of functional mechanisms of SPDL1 in cancers." (PMID 35093072, 2022). "SPDL1 was abnormally expressed in pan-cancer tissues based on data obtained from the TCGA and XENA-TCGA-GTEx databases." (PMID 35664322, 2022). "To analyze the role of SPDL1 in cancers, we performed an enrichment analysis of SPDL1-related genes and proteins." (PMID 35093072, 2022). "The pan-cancer data from the TCGA database were sorted which showed that SPDL1 was abnormally expressed in several matched cancer tissues." (PMID 35664322, 2022).